EGFR (epidermal growth factor receptor)
Diseases named in the same sentence as EGFR in open-access papers (continued):
Sharing a sentence is not in itself a finding about the gene and the disease.
non-small cell lung carcinoma (continued). "Several trials have shown the beneficial effect of epidermal growth factor receptor tyrosine kinase inhibitors (EGFR-TKIs) in advanced non-small cell lung cancer patients (NSCLC) harboring activating EGFR mutations leading to the adoption of EGFR-TKI as standard treatment in this population." (PMID 28359318, 2017). "Similarly, gefitinib and erlotinib prolong survival for patients with non-small cell lung cancer by inhibiting overactive epidermal growth factor receptor caused by activating mutations in EGFR." (PMID 28555425, 2017). "Therefore, we conducted this retrospective study to elucidate the efficacy of these three tyrosine kinase inhibitors as first-line treatment in patients with EGFR-mutated non-small cell lung cancer." (PMID 27935868, 2017). "One must bear in mind that whilst some of the MTA target molecular alterations that have not been proven to be drivers for any specific disease (e.g. PI3KCA mutations), other MTA target clear defined oncogenic aberrations (e.g. EGFR mutations in non-small cell lung cancer –NSCLC-)." (PMID 27835915, 2017). "Earlier reports have shown that vorinostat is effective in correcting splicing in epidermal growth factor receptor (EGFR)-mutated non-small cell lung cancer (NSCLC) cell lines harboring the BIM deletion polymorphism, and overcoming BIM deletion polymorphism-mediated EGFR TKI resistance." (PMID 28301600, 2017). "Direct sequencing and amplification refractory mutation system (ARMS) are commonly used to detect epidermal growth factor receptor (EGFR) mutation status in patients with non-small-cell lung cancer to inform the decision-making on tyrosine kinase inhibitors treatment." (PMID 28938658, 2017). "When epidermal growth factor receptor (EGFR) gene mutation-positive non-small cell lung cancer (NSCLC) acquires resistance to the initial tyrosine kinase inhibitor (TKI) treatment, reassessing the tumor DNA by re-biopsy is essential for further treatment selection." (PMID 29212495, 2017). "Of the 1006 patients diagnosed with stage IIIb and IV non-small cell lung cancer in the study period, 448 (44.5%) had EGFR-activating mutations and received first-line therapy with gefitinib (n = 304, 67.6%), erlotinib (n = 63, 14.3%), or afatinib (n = 81, 18.1%)." (PMID 27935868, 2017). "The recent LUX-Lung 7 trial reported statistically significant benefits in progression-free survival in patients receiving afatinib compared to gefitinib as first-line treatment in patients with non-small cell lung cancer harboring EGFR-activating mutations (HR, 0.73; 95% CI, 0.57–0.95, p = 0.017)." (PMID 27935868, 2017). "Previous studies have suggested that EGFR tyrosine kinase inhibitors are highly effective against mutated-EGFR non-small cell lung cancer given that TKI may increase the binding affinities to these mutant EGFR proteins." (PMID 29110716, 2017). "The standard combination of initial and subsequent treatments of epidermal growth factor receptor (EGFR)-mutated non-small cell lung cancer (NSCLC) patients with solitary brain metastases (BM) remain unclear." (PMID 29037198, 2017). "EGFR was chosen as a candidate gene because EGFR polymorphisms and mutations have been associated with a number of cancers, including anal cancer, colorectal cancer, glioblastoma, and non-small-cell lung cancer." (PMID 28700691, 2017). "Mutations in epidermal growth factor receptor (EGFR) gene activation (19 exon del/L858R) may be a risk factor for brain metastases in patients with non-small cell lung cancer (NSCLC)." (PMID 29228726, 2017). "The epidermal growth factor receptor (EGFR) tyrosine kinase inhibitors (TKIs) significantly improve the outcomes as an initial treatment in non-small cell lung cancer (NSCLC) patients with activating EGFR mutations compared with standard platinum-doublet chemotherapy." (PMID 29163853, 2017).
non-small cell lung carcinoma (continued). "In this study, we used wet and in silico approaches to investigate whether EMT phenotypes are associated to resistance to target therapy in a non-small cell lung cancer model system harboring activating mutations of the epidermal growth factor receptor." (PMID 29262566, 2017). "Most recently, EGFR inhibitors have been shown to down-modulate baseline PD-L1 expression, a prominent immune-checkpoint protein, on selected non-small cell lung cancer cell lines with sensitive EGFR mutations that expressed high baseline level of PD-L1 proteins." (PMID 27467256, 2016). "We recently reported a germline deletion polymorphism in the BIM gene that was sufficient to mediate intrinsic resistance to targeted therapies in cancer, including the examples of imatinib (IM) in CML and EGFR inhibitors in EGFR-mutated non-small cell lung cancer (EGFR-NSCLC)." (PMID 26517680, 2016). "The first- and second-generation epidermal growth factor receptor tyrosine kinase inhibitors (1/2G EGFR-TKIs) gefitinib, erlotinib, and afatinib have all been approved as standard first-line treatments for advanced EGFR mutation-positive non-small cell lung cancer." (PMID 27912760, 2016). "MET overexpression and the EGFR T790M mutation are both associated with acquired resistance (AR) to epidermal growth factor receptor tyrosine kinase inhibitors (EGFR-TKIs) in advanced non-small cell lung cancer (NSCLC)." (PMID 27259997, 2016). "In particular, epidermal growth factor receptor (EGFR)-targeted therapy with tyrosine kinase inhibitors (TKIs) such as erlotinib, gefitinib and afatinib have been effective in a subset of patients with non-small cell lung cancer (NSCLC) harboring EGFR activating mutations." (PMID 26883194, 2016). "Non-small-cell lung cancer (NSCLC) cell lines bearing EGFR, KRAS, BRAF, ALK or RET mutations were found with high level of PD-L1 expression, and this may be correlated with high levels of PI3K/AKT/mTOR pathway activation." (PMID 26919108, 2016). "This relatively high mutation rate of EGFR in CRC may present itself as an opportunity for the use of the non-small cell lung carcinoma tyrosine kinase inhibitors (TKIs) treatment regimes targeting this receptor." (PMID 27146902, 2016). "Non-small-cell lung cancer (NSCLC) patients with activating epidermal growth factor receptor (EGFR) mutations may exhibit primary resistance to EGFR tyrosine kinase inhibitor (TKI)." (PMID 27121209, 2016). "A similar approach could be used to interrogate TCGA data for the predictive value of immune profiles and T-cell infiltration for other monoclonal antibody therapies such as cetuximab in EGFR-mutated non-small cell lung cancer patients." (PMID 27452728, 2016). "Epidermal growth factor receptor tyrosine kinase inhibitors (EGFR-TKIs), gefitinib, erlotinib, and afatinib,are effective therapeutic agents against non-small cell lung cancer (NSCLC) with EGFR-activating mutations, such as the exon 19 deletion and the L858R point mutation." (PMID 27259997, 2016). "Activating somatic mutations in EGFR are prevalent in non-small cell lung cancer (NSCLC) patients." (PMID 27612423, 2016). "Mutations in the EGFR kinase domain cause non-small cell lung cancer." (PMID 27869781, 2016). "In view of the fact that certain non small cell lung carcinoma associated epidermal growth factor receptor mutations keep the receptor constitutively active, the downstream effectors of altered activity of mutant receptors are largely unknown." (PMID 26146591, 2015). "EGFR tyrosine-kinase inhibitor therapy may be the treatment of choice for non-small cell lung carcinoma patients harboring an activating EGFR mutation in the metastatic lesion." (PMID 25663915, 2015). "Moreover, the ability to cause regression of brain metastases in patients with non-small cell lung cancer and EGFR mutations has been well described, suggesting that the agent does have adequate penetration into the CNS to have antitumor activity." (PMID 25784657, 2015).
non-small cell lung carcinoma (continued). "Companion diagnostics associated with favourable drug responses comprised genomic alterations in non-small cell lung cancer (EGFR mutations and ALK rearrangements), breast and gastric cancers (HER2/neu amplification or overexpression), and in melanoma (B-RAF mutation)." (PMID 26446908, 2015). "Screening TNBC/basal-like breast cancer for EGFR mutations may prove useful for directing therapy but, as in non-small cell lung cancer, accompanying mutations in PIK3CA may confer gefitinib resistance." (PMID 25969993, 2015). "In addition, HOXA5 expression was associated with better clinical outcome in non-small cell lung cancer patients with wild-type EGFR." (PMID 25875824, 2015). "However, for research purposes, it is not easy to obtain tumor samples from patients with EGFR mutation-positive non-small-cell lung cancer (NSCLC) that has relapsed after treatment with EGFR-TKIs." (PMID 26334838, 2015). "Resistance to tyrosine kinase inhibitors occurs in treatments of non-small-cell lung cancers (NSCLCs) with EGFR mutations but the mechanisms underlying this acquired resistance are unknown." (PMID 25758528, 2015). "EGFR mutations have been identified in approximately 10–30% of non-small-cell lung cancer (NSCLC)." (PMID 26515464, 2015). "The clinical effectiveness of EGFR targeted therapies, including small molecules directed against the kinase domain such as gefitinib, erlotinib and afatinib, have been proven successful in treating non-small cell lung cancer patients with tumors harboring EGFR kinase domain mutations." (PMID 25826094, 2015). "For example, the National Comprehensive Cancer Network (NCCN) guidelines for non-small cell lung cancer (NSCLC) recommend measurement of genomic alterations in seven different genes (EGFR, ALK, ERBB2 (encodes HER2 protein), BRAF, MET, ROS1 and RET) to guide twelve different matched therapies." (PMID 26474073, 2015). "Afatinib is an oral irreversible ErbB family blocker being investigated as a potential treatment for a variety of solid tumours, including epidermal growth factor receptor (EGFR)-mutation-positive non-small cell lung cancer (NSCLC), and metastatic head and neck cancer." (PMID 24906422, 2014). "A non-small-cell lung cancer (NSCLC) with an EGFR mutation exhibits a good response to EGFR-TKI." (PMID 24555578, 2014). "It has been extensively proved that the efficacy of epidermal growth factor receptor-tyrosine kinase inhibitors (EGFR-TKIs) is superior to that of cytotoxic chemotherapy in advanced non-small cell lung cancer (NSCLC) patients harboring sensitive EGFR mutations." (PMID 25222496, 2014). "In some cases, identification of genetic aberrations is a prerequisite for commencing treatment; for example, identification of EGFR-activating mutations in patients with non-small cell lung cancer is required prior to starting treatments with EGFR tyrosine kinase inhibitors." (PMID 24886394, 2014). "It has been reported that in EGFR mutation-positive (exon 19 deletion) patients with non-small cell lung cancer complicated by LC, a survival rate of 11 months can be achieved with targeted treatment using EGFR-tyrosine kinase inhibitors (TKI) such as gefitinib." (PMID 25364413, 2014). "In addition, EGFR gene mutations have been reported in patients with non-small-cell lung cancer, and the status of these mutations has been correlated with the clinical response to tyrosine kinase inhibitors such as gefitinib." (PMID 24457059, 2014).
non-small cell lung carcinoma (continued). "Afatinib is approved in the major ICH (International Conference on Harmonisation of Technical Requirements for Registration of Pharmaceuticals for Human Use) regions of the USA, EU and Japan for the treatment of patients with non-small cell lung cancer harbouring distinct EGFR activating mutations." (PMID 25432788, 2014). "There have been a number of studies showing that gain of function mutations in the epidermal growth factor receptor (EGFR) gene may cause non-small cell lung cancer (NSCLC)." (PMID 23403410, 2013). "Non-small cell lung cancers (NSCLCs) that harbour activating mutations and/or amplification of the EGFR locus are particularly sensitive to EGFR-tyrosine kinase inhibitors (TKIs) such as gefitinib (Iressa; AstraZeneca International) and erlotinib (Tarceva; OSI Pharmaceuticals)." (PMID 24339922, 2013). "Epidermal growth factor receptor (EGFR) is occasionally mutated in non-small cell lung cancer and heterogeneity in treatment response could result from differences in EGFR mutation status." (PMID 23232551, 2013). "Also, patients with non-small cell lung cancer harboring activating mutations within the kinase domain of EGFR show impressive clinical responses to the EGFR inhibitor gefitinib." (PMID 23785399, 2013). "Patients with advanced non-small cell lung cancer (NSCLC) carrying epidermal growth factor receptor (EGFR) activating mutations benefit from EGFR-tyrosine kinase inhibitor (TKI) treatment, however, most of TKI-treated patients eventually suffer drug resistant after 10-month treatments." (PMID 23769347, 2013). "Likewise, half of all non-small cell lung cancers treated with the EGFR inhibitors gefitinib or erlotinib acquire a second mutation in exon 20 of EGFR that confers resistance." (PMID 24152305, 2013). "Testing for EGFR mutation status is usually performed on the primary specimen that led to a diagnosis of non-small-cell lung cancer as this may be the only available tissue." (PMID 22666589, 2012). "Gefitinib may be a good first choice for patients with orbital non-small cell lung cancer metastasis harboring epidermal growth factor receptor-activating mutations." (PMID 23079208, 2012). "For example, a study of intratumor heterogeneity of EGFR mutations in non-small-cell lung cancer found that tumors that contain both mutation-positive and mutation-negative tumor cells are less responsive to gefitinib than tumors that do not display such heterogeneity." (PMID 22235286, 2012). "The success of molecular-targeted therapy depends on the identification of a landmark to select patients with more benefit from the therapy, such as activating mutation or gene amplification of EGFR in non-small cell lung cancer, and overexpression or gene amplification of HER2 in breast cancer." (PMID 21466710, 2011). "EGFR mutations correlate with improved clinical outcome whereas KRAS mutations are associated with lack of response to tyrosine kinase inhibitors in patients with non-small cell lung cancer (NSCLC)." (PMID 21949883, 2011). "For example, a microfluidic chip-based CTC technology has been developed, which isolates relatively high numbers of CTCs and can be used to non-invasively detect drug-sensitive and -resistant epidermal growth factor receptor (EGFR) mutations from non-small cell lung cancer (NSCLC) patients." (PMID 20461092, 2010). "The receptor tyrosine kinase ErbB2 (Her2/Neu) is overexpressed in 20% of breast cancers; epidermal growth factor receptor (EGFR) is highly expressed in non-small-cell lung cancers; and the FLT3 receptor is mutated in 30% of acute myelogenous leukemias (AML) and other hematological malignancies." (PMID 21049054, 2010). "The assays may also be of use for selection of patients with ERBB2 positive breast cancer or non-small cell lung cancer carrying EGFR mutations." (PMID 20098682, 2010).
non-small cell lung carcinoma (continued). "Similarly, the T790M point mutation in the epidermal growth factor receptor (EGFR) confers resistance to the EGFR tyrosine kinase inhibitors gefitinib and erlotinib, which are used to treat non-small cell lung cancer." (PMID 19893626, 2009). "Interestingly, Gefitinib has been shown to be most effective in ~10% of non-small cell lung carcinoma patients with mutations around the ATP binding domain of the EGFR." (PMID 21892266, 2008). "Gefitinib induced substantial clinical responses and reduced tumour burden in ∼10% of patients with chemotherapy–refractory non-small cell lung cancers; however, the majority of these patients had EGFR mutations that constitutively activated the antiapoptotic protein AKT." (PMID 17533397, 2007). "Non-small cell lung carcinoma (NSCLC) remains one of the most challenging forms of cancer to treat, particularly in the context of EGFR mutations." (PMID 40149368, 2025). "This study aimed to compare the efficacy of first-generation epidermal growth factor receptor (EGFR)-tyrosine kinase inhibitors (TKIs) combined with low-dose bevacizumab(7.5 mg/kg) versus osimertinib as first-line treatment in patients with advanced EGFR-mutated non-small cell lung cancer (NSCLC)." (PMID 40277017, 2025). "Non-small-cell lung cancer (NSCLC) harboring epidermal growth factor receptor (EGFR) mutations may undergo histological transformation into small-cell lung cancer (SCLC) as a mechanism of acquired resistance to EGFR-tyrosine kinase inhibitors (EGFR-TKIs)." (PMID 41149456, 2025). "Similarly, in the APPLE Phase II randomised trial, the detection of EGFR inhibitor resistance variants in non-small cell lung cancer patients receiving EGFR inhibitors allowed for earlier transitions and responses to the third-generation EGFR inhibitor, Osimertinib." (PMID 39934875, 2025). "However, in patients with EGFR-mutated non-small cell lung cancer (NSCLC), the combination of AUY922 (70 mg/m2 once weekly) and erlotinib showed modest efficacy (PR 16%), but the clinical benefit was limited due to an increase in adverse effects, such as night blindness." (PMID 40872476, 2025). "Aberrant EGFR signaling mechanisms, including the overexpression of ligands and receptors, EGFR gene amplification, and activating mutations, have been shown in a number of cancers, such as non-small-cell lung cancer, colorectal carcinoma, breast cancer, and head and neck squamous cell carcinoma." (PMID 38727302, 2024). "EGFR tyrosine kinase inhibitors (TKIs) have transformed the treatment of EGFR-mutated non-small cell lung carcinoma (NSCLC); however, therapeutic resistance remains a clinical challenge." (PMID 38182677, 2024). "For example, the systemic treatment of advanced non-small cell lung cancer remained conventional chemotherapy for several decades until the emergence of TKI therapy following the discovery of several driver mutations including EGFR, ALK, ROS1, MET, RET, BRAF, and ERBB2/HER2." (PMID 39409947, 2024). "Although EGFR signaling has been implicated in CDDP resistance in various cancer types including non-small cell lung cancer (NSCLC), cervical cancer, and OSCC, it remains unclear which specific pathway predominantly contributes to the drug resistance in oral cancer." (PMID 38560690, 2024). "Additionally, ALDH1A3 expression was reported to be enriched in EGFR-mutated non-small cell lung carcinoma cells resistant to the EGFR tyrosine kinase inhibitor erlotinib, suggesting that ALDH1A3-expressing cancer cells are resistant to other treatments beyond chemotherapy." (PMID 36672441, 2023). "We found eight EGFR activating point mutations (22.2%, n = 36) in 5/29 patients (17.2%): six of these were considered rare variants (p.V774M, p.T751I and p.S752Y in exon 19; p.G719S and p.A702D in exon 18; p.E66K in exon 21) that are usually described in non-small cell lung cancer." (PMID 37046732, 2023).